HMGB1 (high mobility group box 1)
Diseases named in the same sentence as HMGB1 in open-access papers (continued):
Sharing a sentence is not in itself a finding about the gene and the disease.
myocardial infarction (75 papers, 2010 to 2025). Gross necrosis of the myocardium, as a result of interruption of the blood supply to the area, as in coronary thrombosis. "In rats with myocardial injury caused by myocardial infarction, the expression of miR-200b-3p and miR-200a-3p is downregulated, and melatonin can regulate the miR-200b-3p/HMGB1 axis to alleviate inflammation and heart failure caused by myocardial infarction." (PMID 40997050, 2025). "Which included HMGB1 mRNA, CK-MBmax, and Tnmax, and found that HMGB1 mRNA remained significantly associated with adverse LV remodeling, independently of myocardial infarct size (β ± SD = 0.23 ± 0.11, p = 0.03)." (PMID 39457420, 2024). "We hypothesized that anti-HMGB1 treatment would ameliorate the oxidative and inflammatory changes associated with myocardial infarction, potentially offering a therapeutic strategy to mitigate cardiac damage." (PMID 41291022, 2025). "Elevated circulating HMGB1 is associated with myocardial infarction in humans." (PMID 37484982, 2023). "Therefore, it can be inferred that the increased risk of myocardial infarction caused by periodontal disease may be related to HMGB-1." (PMID 36923959, 2023). "Another study recognized serum high-mobility group box 1 (HMGB1) as a biomarker for acute myocardial infarction with heart failure." (PMID 40860357, 2025). "Another investigation found that circFoxo3 alleviated myocardial ischemia/reperfusion injury by reducing autophagy, achieved by inhibiting HMGB1 through the suppression of KAT7 in myocardial infarction." (PMID 40045371, 2025). "Compared with experimental myocardial infarction, anti-HMGB1 treatment resulted in a significant reduction in the CD concentration (p < 0.01)." (PMID 41291022, 2025). "This suggests that miR-129-5p, transported through exosomes, can mitigate inflammation in myocardial infarction mice by targeting HMGB1." (PMID 38913049, 2024). "Their findings revealed improved cardiac function, reduced expression of HMGB1 and proinflammatory cytokines, and decreased apoptosis and fibrosis in the cardiac tissue of myocardial infarction mice treated with these exosomes." (PMID 38913049, 2024). "Classic DAMPs in acute myocardial infarction (MI) include high-mobility group protein B1 (HMGB1, amphoterin), heat shock proteins, s100 proteins, and nucleic acids, including mitochondrial DNA." (PMID 39335587, 2024). "In rodent myocardial infarction models, HMGB1 plays a significant role in the pathological remodeling of the left ventricle." (PMID 37484982, 2023). "The function of HMGB1 in thrombosis has only been superficially covered but findings from acute myocardial infarction patients suggested that platelet-derived HMGB1 acts on neutrophils and stimulates the release of NETs." (PMID 37275917, 2023). "Higher HMGB-1 levels are associated with poor outcomes after myocardial infarction (MI)." (PMID 36244983, 2022). "HMGB1 is involved in a wide range of cardiovascular pathophysiology and participates in hypertrophy, myocardial infarction, and remodeling; this subsequently leads to heart failure and pulmonary hypertension." (PMID 35743792, 2022). "In contrast, administration of HMGB1 after myocardial infarction induced by permanent coronary artery ligation improves cardiac performance by promoting tissue regeneration." (PMID 35340325, 2022). "HMGB1 enhances angiogenesis, restores cardiac function and improves survival after myocardial infarction in mice." (PMID 33925132, 2021). "Local administration of HMGB1 peptide promotes tissue regeneration in myocardial infarction or diabetic ulcers by attenuating inflammation and/or promoting angiogenesis." (PMID 34565478, 2021). "High mobility group box 1 (HMGB1) is a ubiquitous and abundant nucleoprotein that plays a key role in many cardiovascular diseases, such as myocardial ischemia/reperfusion injury, myocardial infarction, and heart failure." (PMID 34336950, 2021).
myocardial infarction (continued). "The application of HMGB-1 after myocardial infarction also decreased levels of IL-1, IL-6, IL-10 and vascular endothelial growth factor (VEGF)." (PMID 32403440, 2020). "Experiments on transgenic mice with cardiac-specific overexpression of HMGB1 have shown that the protein enhances angiogenesis, restores cardiac function, and improves survival after myocardial infarction (MI)." (PMID 32214047, 2020). "We compared myocardial infarct size, serum levels of cTnI, and expression of HMGB1, TNF-α, and IL-6 in the myocardium and serum in all groups after 120 min of reperfusion." (PMID 31344138, 2019). "Infection with P. gingivalis after myocardial infarction in mice enhanced myocardial high mobility group box 1 (HMGB1) expression." (PMID 31600905, 2019). "In contrast, administration of HMGB1 after myocardial infarction induced by permanent coronary artery ligation ameliorates cardiac performance by promoting tissue regeneration." (PMID 30306212, 2019). "HMGB1 was previously shown to activate the Wnt/β-catenin signaling pathway in a rat model of myocardial infarction." (PMID 29922171, 2018). "In a mouse model of acute myocardial infarction, overexpression of HMGB1 in cardiac cells or local administration of HMGB1 induced myocardial regeneration, restored cardiac function, and improved survival." (PMID 26347745, 2015). "In conclusion, serum HMGB1 levels are elevated in patients with coronary artery disease, particularly in those with acute myocardial infarction." (PMID 23935732, 2013). "Serum HMGB1 levels in patients with acute myocardial infarction were higher compared with those in patients with unstable and stable angina pectoris (77.53±6.86 vs. 63.67±8.6 and 44.39±9.01 μg/l, respectively; all P<0.01)." (PMID 23935732, 2013). "The HMGB1 levels in the acute myocardial infarction group were higher than those in the unstable and stable angina pectoris groups." (PMID 23935732, 2013). "The main findings of the current study were that serum HMGB1 levels are elevated in patients with coronary heart disease, particuarly in those with acute myocardial infarction." (PMID 23935732, 2013). "In conclusion, serum HMGB1 levels were elevated in patients with coronary artery disease, particularly in those with acute myocardial infarction." (PMID 23935732, 2013). "Serum HMGB1 levels in patients with acute myocardial infarction were higher compared with those in patients with unstable and stable angina pectoris (77.53±6.86 vs. 63.67±8.6 and 44.39±9.01 μg/l, respectively; both P<0.01)." (PMID 23935732, 2013). "Our laboratory has shown that HMGB1 administration, acutely after myocardial infarction, induces cardiac progenitor cell proliferation and differentiation, myocardial regeneration and an improvement in cardiac performance." (PMID 21731608, 2011). "The present findings are consistent with this context-dependent paradigm, suggesting that modulation of HMGB1 activity may shift the balance between tissue injury and repair following myocardial infarction." (PMID 41291022, 2025). "Decreased levels of CK and LDH were also observed, along with a notable reduction in myocardial infarct size.Evidence suggests that these protective effects may involve the HMGB1 signaling pathway, which plays a central role in early inflammatory responses." (PMID 40672380, 2025). "In myocardial infarction, HMGB1 seems to both induce inflammatory reactions, which could increase tissue damage, and myocardial regeneration by enhancing angiogenesis." (PMID 39194749, 2024). "In addition, one animal study had found that P. gingivalis can enhance the expression of high mobility group box 1 (HMGB1) in mice after myocardial infarction." (PMID 36923959, 2023). "Whilst multiple DAMPs are released by dying cardiomyocytes, particularly after myocardial infarction and include mitochondrial DNA (mtDNA), the chromatin protein high mobility group box 1 (HMGB1) and S100 proteins, their precise roles in fibrosis are still unclear." (PMID 36483558, 2022).
myocardial infarction (continued). "Several trials were able to show that not only iVNS dampens inflammatory reactions, but also taVNS leads to decreased serum levels of IL 1β, IL 6, TNF-α, and HMGB-1 in patients with myocardial infarction or atrial fibrillation compared to sham-stimulated controls." (PMID 34599686, 2022). "In an experimental model of myocardial infarction induced by permanent coronary ligation, injection of fr-HMGB1 reduces infarct area and improves cardiac function because it is able to promote angiogenesis and differentiation of resident cardiac stem cells (CPCs) into cardiomyocytes." (PMID 35340325, 2022). "In addition to the Kubota group, which used HMGB1 transgenic mice to show that cardiac nuclear HMGB1 exerts protective effects on myocardial infarction, cardiac hypertrophy, and HF, many studies have shown that HMGB1 is an independent predictor of death in HF." (PMID 33680285, 2021). "In addition, ejection fraction measured by echocardiography improved in the locally HMGB-1 treated animals after myocardial infarction." (PMID 32403440, 2020). "In the present study, we found that after adding LY294002 treatment to the group treated with a high dose of Sal B, the size of myocardial infarction, the levels of myocardial necrosis and myocardial inflammation markers and the expression of HMGB1 were significantly increased." (PMID 31853618, 2020). "Transgenic mice with an overexpression of cardiac-specific HMGB-1 were protected against the consequences of myocardial infarction, whereas animals with HMGB1 null mutation are nonviable." (PMID 32403440, 2020). "This study aimed to evaluate whether systemic injection of HMGB1 fragment could promote tissue repair in a rat model of myocardial infarction (MI)." (PMID 32275672, 2020). "Another interesting article showed that mice with overexpression of HMGB1, after ligation of left anterior descending coronary artery, had better survival rates, a smaller size of myocardial infarction, and cardiac remodeling and dysfunction were prevented, compared to control mice." (PMID 31835864, 2019). "Besides HMGB1, HMGB2 is associated with myocardial infarction severity and induces cell apoptosis in myocardial ischemic animals." (PMID 30886640, 2019). "Furthermore, in diabetic mice with post-myocardial infarction remodeling, there are increased levels of HMGB1 with enhanced inflammation and fibrosis and it has been demonstrated that knockdown of HMGB1 and RAGE genes reduces inflammation and infarct size." (PMID 31835864, 2019). "For example, although HMGB1 triggers detrimental inflammation soon after certain injuries, it functions later as a repair molecule, mediating myocardial regeneration after myocardial infarction by inducing resident cardiac c-kit+ progenitor cell proliferation and differentiation." (PMID 26499847, 2015). "A previous study demonstrated that left ventricular remodeling and dysfunction may be restricted and survival improved significantly in transgenic mice with a high expression level of HMGB1 4 weeks after the onset of myocardial infarction." (PMID 23935732, 2013). "Besides its putative adverse effects in MI/R, it must be noted, that during recovery from myocardial infarction exogenous HMGB1 injection has been shown in a number of studies to prevent adverse remodelling and improve cardiac function." (PMID 24371373, 2013). "Studies have shown that serum HMGB1 levels are elevated in experimental and clinical acute myocardial infarction, which may indicate an important role in the healing process of the infarcted myocardium." (PMID 23935732, 2013). "On the other hand HMGB1 exhibits beneficial effects in a model of myocardial infarction." (PMID 22792152, 2012).
myocardial infarction (continued). "Another mechanism of neutrophil activation is the expression and presentation of HMGB1 on activated platelets, which recruits leukocytes and induces, among other actions, the formation of neutrophil extracellular traps in both animal models and patients following acute myocardial infarction." (PMID 38958135, 2024). "In the context of myocardial infarction, fr-HMGB1, once released in the oxidizing environment generated after MI by ROS production, becomes disulphide HMGB1 first and ox-HMGB1 later." (PMID 35053332, 2022). "In 2017, C-MSCs were used to investigate the role of High Mobility Group Box 1 (HMGB1) in cardiac remodeling after myocardial infarction (MI), since this protein, which exists in two redox forms, regulates tissue repair after injuries." (PMID 32887493, 2020). "Conversely, in rats with experimental myocardial infarction, inhibition of HMGB1 promoted thinning and expansion of the infarct scar and marked hypertrophy of the non-infarcted area, maybe through impairment of the infarct-healing process depending on HMGB1 function." (PMID 31835864, 2019). "Inhibition of the high-mobility group box-1 (HMGB1)/TLR4/TRAF6/NF-κB signaling pathway is beneficial for treatments of MI/R injury and acute myocardial infarction (AMI)." (PMID 32038243, 2019). "Additionally, an important role for platelet-exposed high mobility group box 1 (HMGB1) in activating autophagy-mediated NET generation has been suggested in a study using thrombi biopsies from acute myocardial infarction patients, pharmacologic and genetic tools." (PMID 30234114, 2018). "HMGB1 injection into the mouse heart, acutely after myocardial infarction (MI), improves left ventricular (LV) function and prevents remodeling." (PMID 21731608, 2011). "The present study demonstrated that myocardial infarction induces significant alterations in NOS activity and redox homeostasis, which are partially ameliorated by the administration of the anti-HMGB1 protein." (PMID 41291022, 2025). "This protective effect was characterized by a reduction in myocardial infarction size, decreased expression of myocardial injury markers, attenuated cell apoptosis, enhanced PI3K/Akt expression, and inhibition of high mobility group box 1 (HMGB1) expression." (PMID 39741628, 2024). "In acute myocardial infarction, increased expression of RAGE and its interaction with AGEs, HMGB1, and S100 induce cardiomyocyte apoptosis by activating the MAPK pathway." (PMID 33568752, 2021). "This study demonstrates that TLR9 is essential for the repair of infarcted myocardium and interaction of HMGB1 and TLR9 is involved in the survival of myocardial cells, wound healing, and angiogenesis after myocardial infarction." (PMID 31209243, 2019). "Study has shown that both HMGB1 and HMGB2 levels increase in the serum of myocardial infarction patients, ischemic myocardial tissues, and hypoxic H9C2 cells." (PMID 30886640, 2019). "Myocardial infarct sizes, histological scores, levels of circulating and myocardial IL-6 and TNF-α, the expression of HMGB1, TLR4, MyD88 and NF-κB, and the degradation of IκB were significantly increased in the I/R group compared with the sham group (P<0.01)." (PMID 28222157, 2017). "TLR4 is also activated by several endogenous ligands associated with tissue injury such as High-Mobility Group Box 1 Protein (HMGB1), HSP60/70, and hyaluronan in response to myocardial infarction (MI)." (PMID 26030867, 2015). "In the current study, we measured serum HMGB1 levels and determined their correlation with serum hs-CRP and cTnI levels in patients with stable and unstable angina pectoris, as well as acute myocardial infarction." (PMID 23935732, 2013). "Patients with myocardial infarction had HMGB-1 levels of 7.313 ± 1.650 ng/mL and those without myocardial infarction 5.553 ng/mL ± 2.728 (p = 0.0001)." (PMID 36244983, 2022).
myocardial infarction (continued). "Our results provide further support for the dual role of HMGB1 in the pathophysiology of myocardial infarction and highlight its potential as a therapeutic target not only for reducing inflammation and oxidative stress, but also for limiting adverse fibrotic remodeling of the myocardium." (PMID 41291022, 2025). "After myocardial infarction, high-mobility group box 1 (HMGB1) has a crucial role—i.e., as a DAMP—in mediating the post-MI inflammatory cascade." (PMID 39457420, 2024). "Therefore, HMGB1 affects progression and severity of CAD and it could be involved in major adverse cardiac events (MACE) in diabetic patients after acute myocardial infarction; however, further studies are needed to verify this hypothesis." (PMID 31835864, 2019). "During 40 min of LCA occlusion without reperfusion, NC attenuated ischemic myocardial infarct size by 50% compared to normothermic control as defined by TTC-blue staining and significantly decreased CP levels of cTnT, cfDNA and HMGB1." (PMID 35837603, 2022).